CCDC85B (coiled-coil domain containing 85B)
Description:
Functions as a transcriptional repressor. May function in adipocyte differentiation, negatively regulating mitotic clonal expansion (By similarity). Plays a role in cell-cell adhesion and epithelium development through its interaction with proteins of the beta-catenin family (By similarity). (Microbial infection) Plays a role in hepatitis delta virus (HDV) genomic replication.
Synonyms: DIPA
Tractability: PROTAC: its protein half-life has been measured.
Gene: Protein-coding gene on chromosome 11 (65,890,673 to 65,891,635, forward strand). Ensembl gene ENSG00000175602.
Subcellular location: Nucleus; Cytoplasm, cytoskeleton, microtubule organizing center, centrosome; Cell junction, adherens junction
Gene Ontology:
Molecular function: delta-catenin binding; protein binding
Biological process: negative regulation of cell growth; negative regulation of DNA-templated transcription; negative regulation of fat cell differentiation
Cellular component: adherens junction; centrosome; nucleus
Genetic constraint (gnomAD): Loss-of-function variants: 8 observed, 5.18 expected, observed/expected ratio (o/e) 1.54, 90% interval 0.85 to 1.94. That is too few expected variants to judge how well the gene tolerates losing a copy. Missense variants: 217 observed, 200.95 expected, observed/expected ratio (o/e) 1.08, 90% interval 0.97 to 1.21. Synonymous variants: 118 observed, 95.43 expected, observed/expected ratio (o/e) 1.24, 90% interval 1.06 to 1.44.
Homologues: Orthologues: chimpanzee CCDC85B (99% identical), macaque CCDC85B (99% identical), mouse Ccdc85b (99% identical), rat Fosl1 (99% identical), dog CCDC85B (98% identical), pig CCDC85B (98% identical), tropical clawed frog ccdc85b (63% identical), zebrafish ccdc85b (58% identical), Caenorhabditis elegans picc-1 (31% identical). Paralogues in human: CCDC85C (51% identical), CCDC85A (45% identical).
Diseases named in the same sentence as CCDC85B in open-access papers:
CCDC85B is named in the same sentence as 13 diseases in open-access papers, as found by Europe PMC text mining. Sharing a sentence is not in itself a finding about the gene and the disease. The quoted sentences say what the papers report.
aneurysm (2 papers, 2021 to 2022). Bulging or ballooning in an area of an artery secondary to arterial wall weakening. "Some gene expression in whole blood from the lumen of unruptured IA, such as CCDC85B, was associated with aneurysm size and AWE on HR-VWI, which may be a good candidate marker for identifying higher rupture risk IA." (PMID 35669880, 2022). "Furthermore, our Pearson correlation analysis showed that some of genes (namely, ST6GALNAC1, TIFAB, and CCDC85B) may be informative in assessing IA risk, as their intraluminal expression was related to aneurysm size, IA wall enhancement, or both." (PMID 34441376, 2021).
lung cancer (2 papers, 2021 to 2023). A malignant neoplasm involving the lung. "CCDC85B also promotes non‐small cell lung cancer cell proliferation and invasion." (PMID 36822595, 2023).
Alzheimer disease (1 paper, 2023). A progressive, neurodegenerative disease characterized by loss of function and death of nerve cells in several areas of the brain leading to loss of cognitive function such as memory and language. "Interestingly, abnormal expression patterns for all of them have already been detected either in ALS patients [MIR16, CCDC85B] or in Alzheimer’s Disease patients (GJA5)." (PMID 36694130, 2023).
Down syndrome (1 paper, 2016). "Also, we find that CCDC85B is expressed in the brain, and its expression levels are also disturbed in Down Syndrome." (PMID 27404227, 2016).
hepatocellular carcinoma (1 paper, 2019). A malignant tumor that arises from hepatocytes. "Given that co-infections with hepatitis delta virus (HDV) and hepatitis B virus (HBV) accelerate the development of hepatocellular carcinoma (HCC), one should also note that hMOB1 can associate with CCDC85B (aka DIPA), which is known to play a role in HDV replication." (PMID 31185650, 2019).
non-small cell lung carcinoma (1 paper, 2020). A group of at least three distinct histological types of lung cancer, including non-small cell squamous cell carcinoma, adenocarcinoma, and large cell carcinoma. "It is known that CCDC85B is overexpressed in the tumor sample of non-small cell lung cancer patients and that CCDC85B takes a crucial part in activation of β-catenin." (PMID 33133158, 2020).
retinal degeneration (1 paper, 2021). Degeneration of the retina. "In the group of slow adapters, we identified several downregulated genes that are involved in the development and/or progression of retinal degeneration (Cebpb, Egr4, and Ier5l) or apoptosis (Nrtn, Ccdc85b, Junb and Jund)." (PMID 34404875, 2021).
cancer (2 papers, 2020 to 2021). A tumor composed of atypical neoplastic, often pleomorphic cells that invade other tissues. "To validate whether the candidate targets can actually interrupt cancer progression, we perform in vitro knockdown of CCDC85B and PTTG1 using siRNA and examine the changes of the growth rate and transcriptomic levels." (PMID 33133158, 2020).
CCDC85B also shares sentences with these, for which no sentence is quoted: infection (2 papers); tumor (2); Fever (1); Lyme disease (1); relapsing fever (1).